CD44 (CD44 molecule (IN blood group))
Diseases named in the same sentence as CD44 in open-access papers (continued):
Sharing a sentence is not in itself a finding about the gene and the disease.
cancer (continued). "CD44 has been widely used as a marker for CSCs and it has been implicated in the adhesion, motility, proliferation, and cell survival of several cancers." (PMID 29123181, 2017). "The in vitro cytotoxicity assay indicated that GzmB-encapsulated nanogels had targeted toxicity against CD44-overexpressing HCT-116 cancer cells, while CD44-deficient cells showed little cytotoxic effect." (PMID 28181831, 2017). "Recently, a serious of studies demonstrated the diagnostic and prognostic values of CD44 expression in human cancers including GC." (PMID 28415792, 2017). "On the other hand, using CAFs derived from CD44-deficient mice, we demonstrated that CD44 expressed on CAFs induces stemness and drug resistance in cancer cells." (PMID 28878389, 2017). "CD44, a transmembrane glycoprotein, was initially identified as a receptor for hyaluronic acid, and high CD44 expression was associated with cancer stem cells and epithelial-mesenchymal transition." (PMID 28030801, 2017). "Ezrin also takes part in several signaling pathways, such as Wnt/β-catenin, PI3K/Akt and CD44, all of which are associated with cancer progression." (PMID 29190988, 2017). "CD44 expression has been identified in a variety of tissues and malignant tumors, while CD44 variant isoforms are thought to interfere with cellular growth and metastatic potential of various tumors." (PMID 28421110, 2017). "Significantly, molecular targeting of SMAD5 expression was linked to inhibition of a CD44+/CD24-/PROCR+ cancer stem cell-like phenotype and low ALDH1 activity." (PMID 29207686, 2017). "Recent studies have underscored the importance of the CD44 variant (CD44v) isoforms in mediating E-selectin binding of a number of cancer cell lines." (PMID 28515724, 2017). "Many studies have shown the association of CD44 polymorphisms with cancer risk prediction and prognosis." (PMID 27323782, 2016). "Here, a comprehensive meta-analysis was performed to derive a more precise estimation of the relationship between CD44 polymorphisms and the susceptibility to cancer." (PMID 28000766, 2016). "CD44 is a common HA-receptor and has been linked to cancer cell attachment and transformation following HA binding." (PMID 27405751, 2016). "Overall, odds ratios (OR) calculated with 95% confidence intervals (CI) identified a significant association between CD44 polymorphism rs13347 and cancer susceptibility under all genetic models." (PMID 28000766, 2016). "Here, a meta-analysis was performed to systematically evaluate associations between CD44 polymorphisms and cancer susceptibility." (PMID 28000766, 2016). "Based on our analysis, we suggest significant role of CD44 variants (rs13347, rs187115 and rs11821102) in modulating individual's cancer susceptibility in Asians." (PMID 27521214, 2016). "It is well documented that particular CD44 variants are involved in pathophysiology of several malignant tumors." (PMID 27505250, 2016). "No any statistically significant association was found between CD44 polymorphisms (rs10836347, rs11821102, rs13347, rs1425802, rs353639, rs713330 and rs187115) and overall cancer risk in all the five genetic models." (PMID 27738347, 2016). "Relationships between CD44 polymorphisms and cancer risk have been widely investigated previously, whereas results derived from these studies were inconclusive and controversial." (PMID 27738347, 2016). "CD44 standard (CD44s) and variant (CD44v) isoforms are aberrantly expressed in various cancers and their interaction with HA influences cell migration and homing." (PMID 27507056, 2016). "Among the polymorphisms widely researched for risk factors associated with cancers, CD44 has become a common target gene." (PMID 27738347, 2016). "The level of CD44 expression is associated with more cancer metastasis and lower overall patient survival." (PMID 26840024, 2016).
cancer (continued). "When the data were stratified based on genotyping method, CD44 rs13347 polymorphism was found to be associated with an increased risk of cancer in the MassArray group in all the five genetic models." (PMID 27738347, 2016). "Subsequently, we investigated the CD44v3 and v6 isoforms of CD44 given their association with the cancer cell phenotype." (PMID 27379207, 2016). "In summary, our study suggests CD44 polymorphism rs13347 can serve as a risk factor for cancer, particularly in Chinese." (PMID 28000766, 2016). "Genetic variants of CD44 have been shown to be associated with susceptibility to various cancers; however, the results are confounding." (PMID 27521214, 2016). "They payed attention to the association of CD44 rs13347 genetic polymorphism and cancer risk, and their ethnicity was restricted to Asians." (PMID 27738347, 2016). "Secondly, further studies are warranted to evaluate the effects of CD44 polymorphisms on cancer risk in different ethnicities." (PMID 27738347, 2016). "CD44, a complex transmembrane glycoprotein, was found to be closely associated with the development of various solid tumors in terms of cancer stemness and epithelial-mesenchymal transition (EMT)." (PMID 27686492, 2016). "We further analyzed cancer stem cell markers, CD44, CD24 and CD133, associated with aggressive cancer types and poor prognosis in CRC." (PMID 27411517, 2016). "In the present meta-analysis, we found that CD44 SNPs significantly modulate the risk of cancer in Asians." (PMID 27521214, 2016). "Considering the important role of CD44 in carcinogenesis, several studies have explored the role of genetic variants of CD44 in cancer susceptibility, prognosis and chemotherapeutic response in various human cancers." (PMID 27521214, 2016). "Apart from the direct role played by CD44 activation in cancer, the expression of additional specific variants as v6 and v3 has also been reported in GC." (PMID 27409642, 2016). "We conducted present meta-analysis aiming to explore the association between CD44 polymorphisms and cancer risk." (PMID 27738347, 2016). "It has been shown that the reduction of CD44 in cancer stem cells caused them to differentiate into non-cancer stem cells." (PMID 27465541, 2016). "Standard isoform of CD44 is expressed almost ubiquitously, while splice variants are only expressed in some epithelia and carcinomas." (PMID 27521216, 2016). "Accordingly, CD44 has been implicated in cancer stem cell maintenance during gastric carcinogenesis." (PMID 25331984, 2015). "In conclusion, changing the perspective of CD44 expression from that of a simple marker to a protein, which causes cancer growth and progression, will pave the way for future therapeutic intervention." (PMID 25954275, 2015). "CD44, an adhesion molecule that binds to HA, has been implicated in cancer cell migration, invasion and metastasis." (PMID 26005723, 2015). "It must be noted that CD44+CD24+ expression pattern proposed is what we proposed above to be a hallmark of hybrid E/M cells in many cancer subtypes." (PMID 26258068, 2015). "Among various GAGs and PGs, much research has demonstrated the ability of HA to target cancer cells overexpressing the HA receptor CD44, in particular its variants, and that HA interaction with CD44v augments cancer pathobiology." (PMID 26448753, 2015). "CD44 is the principal cell adhesion receptor expressed in cancer cells and implicated in cancer cell migration, invasion, and metastasis." (PMID 26347743, 2015). "Other researchers, particularly in the cancer field, have demonstrated that the CD44 variant isoforms can have distinct modes of action and divergent functions (61, –, 64)." (PMID 25716319, 2015). "The hyaluronic acid receptor CD44 and its many isoforms are associated with a wide variety of cell types including epithelial, mesenchymal and CSCs (cancer stem cells)." (PMID 25850653, 2015).
cancer (continued). "LMW HA interactions with CD44 are associated with certain pathological conditions, including inflammation, cancer, and induction of angiogenesis." (PMID 25999946, 2015). "In our previous work we showed that a membrane protein implicated in cancer metastases, CD44, activates the expression of a protein known to generate drug resistance, P-glycoprotein (P-gp), also known as the ABCB1 transporter." (PMID 26299618, 2015). "The CD44 variant isoform expressed in cancer stem cells interacts with xCT, a subunit of cystine/glutamate antiporter, promotes glutathione synthesis and increases the cellular GSH level." (PMID 26666373, 2015). "The present chapter will review the works that describe the utilization of GAGs in delivery of molecules for therapeutic purposes and highlights new possibilities for modulating HA interactions with CD44 variants (CD44v) for therapeutic control of cancer." (PMID 26448753, 2015). "Expression of CD44 has been found to be associated with chemoresistance and recurrence during cancer metastasis and progression." (PMID 26079799, 2015). "CD44 mediates the adhesion and dissemination of immune and cancer cells through its association with hyaluronan." (PMID 26347743, 2015). "Activation of CD44 has been seen to promote multidrug resistance (MDR) in cancer cells, which is a hallmark of therapeutic resistance." (PMID 26322272, 2015). "Altogether, these results indicate that NGF induces association between TrkA and CD44 at the plasma membrane in cancer cells of various origins." (PMID 25840418, 2015). "Although 21.7% of control CaSki cells were CD44+/CD24−, KIAA1199 deficiency dramatically decreased the pool of cancer stem cells as only 2.4% to 6.3% were CD44+/CD24−, depending on the efficiency of the shRNA-mediated depletion of KIAA1199." (PMID 25366117, 2014). "Despite the important role of CD44 in cellular processes and cancer, the mechanism underlying CD44 up-regulation in cancers remains poorly understood." (PMID 25184276, 2014). "Recent studies have suggested the pivotal role of CD44 in HCC, and the effect of CD44 polymorphisms on human cancer susceptibility has been documented and described in various cancer studies." (PMID 24971320, 2014). "The intrinsic role of actin reorganisation in cellular adhesion and migration underlies why dysregulation of CD44-based signalling has been associated with the pathophysiological manifestations of cancer dissemination and metastasis." (PMID 24512624, 2014). "In particular, matrix HA interaction with CD44 in cancer cells have been strongly implicated in the development of chemoresistance." (PMID 24606718, 2014). "One distinctive CD44 isoform, so-called pMeta-2 and containing the various exons 6 and 7, has drawn attention since it is associated with cancer aggressiveness and metastatic behavior." (PMID 24122205, 2014). "The involvement of CD44 as the adhesive molecule on senescent ECs is surprising as it has thus far been largely associated with cancer stem cells." (PMID 25059316, 2014). "Two HA receptors are strongly implicated in the cell signaling cascades associated with cancer initiation and progression: these are CD44 (cluster of differentiation 44) and the receptor for hyaluronic acid-mediated motility (RHAMM)." (PMID 24642908, 2014). "CD44 represents a marker for cancer initiating cells in HNC, and is associated with high tumorigenicity." (PMID 25485633, 2014). "CD44 is a complex family of molecules, associated with aggressive malignancies and cancer stem cells." (PMID 24122205, 2014). "Recently, Hideyuki Saya's group reported that cancer stem cells in certain cancers present CD44 variant 8-10 (CD44v) isoform on the plasma membrane, which stabilizes the cystine/glutamate transporter (antiporter; xCT), leading to increased GSH." (PMID 25221514, 2014). "Regarding HA, interactions between HA and its major cell surface receptor, CD44, have raised interests on the basis of influencing on CD44 variants (CD44v) of cancer cells." (PMID 26056582, 2014).
cancer (continued). "Previous studies have determined that LSR and CD44 have multiple variants/isoforms that occur in cancer." (PMID 24990559, 2014). "ARID3B induced expression of genes associated with metastasis and cancer stem cells (CD44, LGR5, PROM1 (CD133), and Notch2)." (PMID 25327563, 2014). "Recent studies have focused on the diagnostic and prognostic significance of CD24 and CD44 expression in human cancers." (PMID 25212506, 2014). "Among the CD44 variant isoforms, variant isoform v4–v7 are thought to be carcinoma-associated variants." (PMID 24727741, 2014). "The promotion of carcinogenesis and metastasis by carcinoma-specific complexes, comprised of EpCAM with CD44 variants and claudin-7, has been demonstrated in several malignancies." (PMID 24727741, 2014). "Although expression of variant CD44 exons has historically been associated with cancer metastasis, the picture regarding CD44 alternative splicing in cancer is complex." (PMID 23935626, 2013). "In the present study, we showed that IL-6 deficiency attenuated the expression of CD44 in in vivo gastric tumorigenesis model, suggesting the relationship among IL-6, CD44, and cancer stem cells." (PMID 23593346, 2013). "The N- and C-termini of the CD44 protein are encoded by constitutive exons, but the CD44 gene also contains an internal block of 10 consecutive internal alternative exons which are differentially regulated during development and in cancer." (PMID 23935626, 2013). "CD44 expression has been associated with up-regulation of other cancer-associated factors such as transforming growth factor-beta (TGF-β), genes associated with WNT signaling, cell adhesion molecules, and chemokines." (PMID 23314952, 2013). "CD44 is essential to the physiological activities of normal cells, but they are also associated with the pathologic activities of cancer cells." (PMID 23822148, 2013). "CD44 molecules with variant exon insertion have been found in blood cells, various normal tissues, and epithelial cancer cells." (PMID 23800986, 2013). "Future studies on CD44 molecules and variant exon 9 are warranted for elucidating basic concepts of cancer propagation and drug resistance." (PMID 23800986, 2013). "LOX is an essential component of the CD44-Twist signaling axis, in which extracellular hyaluronan causes nuclear translocation of CD44 in the cancer cells, thus, triggering LOX transcription by associating with its promoter." (PMID 26237148, 2013). "Analysis of the efficacy of radio-chemotherapy showed that an extensive expression of stem cell markers, that is, integrin-β1, Oct4 and CD44+, by cancer cell was linked with significantly poorer local progression-free interval." (PMID 22333601, 2012). "In this study, an extensive presence of CD44+ cancer cells in locally advanced HNSCC was directly linked with increased proliferation index." (PMID 22333601, 2012). "CD44 gene often undergoes alternative splicing to encode different proteins in different cancer subtypes, displaying its multifaceted expression." (PMID 22693526, 2012). "Studies have shown that CD44 is implicated in several cancer processes including cell growth, adhesion, invasion, and metastasis." (PMID 22679501, 2012). "Both RHAMM and CD44 expression levels have been linked to progression of a number of cancers, including PCa." (PMID 23166824, 2012). "Recent studies have shown that high expression of CD44 in certain types of tumors is associated with the hematogenic spread of cancer cells." (PMID 23112867, 2012). "CD44 is a major cell adhesion molecule expressed in cancer cells and implicated in cancer cell adhesion, migration, and metastasis." (PMID 22253629, 2012).
cancer (continued). "CD44 has been recently identified as one of the cellular surface markers associated with cancer stem cells (CSCs) in several types of tumors." (PMID 23031740, 2012). "There is now considerable evidence that CD44 expression is linked to cancer-initiation cells (CIC) and stem- or progenitor cells." (PMID 24212937, 2011). "High CD44 levels have been associated with unfavorable prognosis in a variety of cancers including those of the breast, stomach, head and neck, biliary tract, and prostate." (PMID 21541039, 2011). "CD44 plays an important role in tissue integrity and is involved in multiple functions associated with cancer progression such as cell migration, resistance to apoptosis and presentation of growth factors and proteases." (PMID 22069487, 2011). "It is likely that the loss of CD44 reactivity from these sites reflect localized CD-44 shedding, which is dependent on MMPs and promotes cancer cell migration and invasion." (PMID 21829496, 2011). "We found a marker of epithelial-mesenchymal transition, CD44, upregulated in response to functional loss of E-cadherin in esophageal cell lines and cancer." (PMID 22069487, 2011). "Many cancer cell types as well as their metastases express high levels of CD44 and/or CD44 variants." (PMID 21317983, 2011). "In human cancer, splice variants of CD44 were frequently identified in advanced stages of tumorigenesis." (PMID 21915300, 2011). "Since CD44 variants are known to play a causal role in metastasis in other cancers, therefore the expression of CD44 variants CD44v3, CD44v6 and CD44v10 has been studied in primary tumor and lymph node samples from HNC patients." (PMID 24212622, 2011). "The invasive behavior of UC-associated carcinoma is more associated with CD44 cleavage than with basement membrane disruption or sialyl-Lewis-antigen alteration." (PMID 21473743, 2011). "CD44 extracellular domain showed lower expression in UC-associated carcinoma than in sporadic carcinoma, in both the well-differentiated category and the poorly differentiated category (P = 0.010, P < 0.001, respectively) in invasive fronts." (PMID 21473743, 2011). "In the present study, CD44 extracellular domain expression was significantly lower in UC-associated carcinoma than in its sporadic counterparts." (PMID 21473743, 2011). "When the lesions were compared with sporadic carcinomas considering differentiation grade, reduced expression of CD44 extracellular domain in UC-associated carcinoma was apparent." (PMID 21473743, 2011). "The expression of CD44 and its variants is associated with the progression of several cancers, although this remains controversial for CaP." (PMID 20736947, 2010). "These include three novel intron retentions in CD44, a gene in which isoform variations have been previously associated with the metastasis of several cancers." (PMID 20700505, 2010). "Mitogen-activated protein kinase pathways and paracrine calcitonin are two common factors linked to dysregulated expression and splicing of CD44 in cancer." (PMID 18793421, 2008). "The expression of MMPs and variant CD44 (vCD44) correlates strongly with cancer cell invasiveness and metastasis." (PMID 17343740, 2007). "Splicing variants of CD44 (CD44v) are increasingly recognised as metastasis-promoting factors in rodent and some human cancers." (PMID 7541233, 1995). "CD44, a cell adhesion molecule, is known to play a role in cancer cell adhesion, migration, and invasion, with its overexpression associated with more aggressive cancer phenotypes." (PMID 40693234, 2025). "Further research on the relationship and mechanisms of action between ESRP1 and CD44 in cancer could lead to the development of new diagnostic markers and treatment targets." (PMID 40046628, 2025). "CD44 has been associated with increased resistance to standard cancer therapy in different cancers." (PMID 41168417, 2025).